AFP (alpha fetoprotein)
Diseases named in the same sentence as AFP in open-access papers (continued):
Sharing a sentence is not in itself a finding about the gene and the disease.
tumor (continued). "Data from the present study demonstrated that AFP proteins was expressed in isolated primary TYST cells, closed TYST cells, pre-transplanted cells, and formed tumor in animals." (PMID 22410253, 2012). "A study from North America has proposed the combination of total tumor volume (TTV) <115 cm3 and AFP <400 ng/mL for the selection of HCC patients, showing that patients exceeding these cut-offs presented very poor post-LT results (below 50% at 3 years)." (PMID 22792474, 2012). "For a small HCC, measurement of both tumor markers is recommended, since DCP is a more specific marker compared with AFP." (PMID 23162601, 2012). "AFP was used as a monitoring marker of closed TYST cells and formed in vivo tumor in the resent study." (PMID 22410253, 2012). "AFP and live Us are widely used for HCC surveillance that must be done every 6 months since this time is considered to be the average time for tumor duplication." (PMID 22655206, 2012). "Alpha-fetoprotein (AFP) and protein induced by vitamin-K absence or antagonist-II (PIVKA-II) also called des-gamma-carboxyprothrombin (DCP) are representative tumor markers for the diagnosis of HCC." (PMID 22957256, 2012). "Patients: HCC vs. cholangiocellular carcinomaTests: GP73, AFP and VEGF expression in tumor, tumor-adjacent and normal liver specimens by immunohistochemistry.Outcomes: no usable data." (PMID 22244200, 2012). "Microarray analysis showed that the average LOH frequency for 10 SNPs located within HPSE gene was 31.6%, three of which were significantly correlated with tumor grade, serum HBV-DNA level, and AFP concentration." (PMID 22952874, 2012). "In another study from the Inter-University Consortium of Rome, 158 HCC patients were stratified according to the total tumor diameter (TTD) >8 cm and AFP >400 ng/mL." (PMID 22792474, 2012). "In multivariate analysis three laboratory parameters (AFP, bilirubin and aP), one clinical (ascites) and two tumor-related parameter (BCLC-tumor extension and number of tumor nodes), respectively remained significant predictors of survival." (PMID 23071507, 2012). "Cell counts, urine analysis, hepatic panel, fasting blood glucose, serum immunoglobulin, tumor markers of carcinoembryonic antigen (CEA), alpha-fetoprotein (AFP), cancer antigen (CA)-199, and prostate specific antigen (PSA) were within normal limits." (PMID 23216913, 2012). "Because any single antigen is ubiquitously expressed in HCC, we selected AFP, GPC-3 and MAGE-1 as target antigens for DC vaccine through the analysis of the tissue array of a tumor tissues obtained from 412 patients with HCC in Korea (data not shown)." (PMID 22971679, 2012). "High expression of dyskerin showed significant association with hepatitis B surface antigen (HbsAg) status (P<0.01), serum alpha-fetoprotein (AFP) levels (P<0.01), and advanced tumor stage (P<0.01)." (PMID 22912812, 2012). "We recorded age, parity, tumor type, stage of cancer, serum levels of tumor markers (CA-125, CA-15.3, CA-19.9, CEA, AFP), and the parameters of blood count, fasting glucose, disease-free survival and overall." (PMID 22577583, 2012). "AFP mRNA is a specific marker of HCC cells in the circulation and several studies have shown a correlation with HCC-aggressive tumour features (nodule size, number, vascular invasion, grading)." (PMID 21912636, 2011). "The tumor marker, CA125, and levels of CEA (carcinoembryonic antigen), AFP (alpha feto-protein) and beta-HCG (human chorionic gonadotrophin) were normal." (PMID 21682901, 2011). "The level of the tumor markers should normalize within a reasonable time (half-life time for HCG: 2 - 3 days; half-life time for AFP: 5 - 6 days)." (PMID 29147233, 2011). "Alpha-fetoprotein (AFP) is an oncofetal antigen that is expressed by more than half of HCC tumors and detectable at elevated levels in the blood and tumor microenvironment in these HCC patients." (PMID 21969837, 2011).
tumor (continued). "Immunohistochemically, many liver specific proteins, including AFP, albumin, transferin, PIVKA (protein induced in the absence of vitamin K), and alpha-1-antitrypsin, have been detected in the tumor cell cytoplasm." (PMID 21914163, 2011). "AFP mRNA and VEGF determinations were significantly related to nodule size, gross vascular invasion, AFP29 ng ml−1, TNM and BCLC staging systems, PST, tumour grading, and Child-Pugh B–C stages." (PMID 21912636, 2011). "In contrast, AFP-specific CD4 T-cell responses are only detected in HCC patients and response was mainly detected in Okuda tumour stage I HCC patients (58.3%) and to a lesser extent in Okuda tumour stage II or III HCC patients (15.8%)." (PMID 20087354, 2010). "Laboratory data upon admission were within normal limits, and tumor markers such as carbohydrate antigen (CA) 19-9, carcinoembryonic antigen (CEA), and alpha-fetoprotein (AFP) were also normal." (PMID 20507577, 2010). "His human chorionic gonadotrophin (HCG) level was elevated (11 mIU/ml) and the other tumor markers, including lactate dehydrogenase (LDH - 240 U/L) and alpha-fetoprotein (AFP - 3 ng/ml), were normal." (PMID 21108777, 2010). "An anti-AFP Th1 response was detected only in HCC patients (58.3% with Okuda stage I tumours and 15.8% with Okuda stage II or III tumours)." (PMID 20087354, 2010). "Overall, the results demonstrate that CD8 T-cell responses to AFP are detectable in control groups (28.5%), as well as in Okuda tumour stage I HCC patients (25%) and Okuda tumour stage II+III HCC patients (31.6%)." (PMID 20087354, 2010). "Alpha-fetoprotein (AFP), AFP lectin fraction L3 (AFP-L3), and des-gamma-carboxy prothrombin (DCP, also known as PIVKA-II) are widely used clinically as serum tumor markers of HCC." (PMID 21192835, 2010). "Elevated preoperative alpha-fetoprotein (AFP) levels, preoperative treatments of HCC, unfulfilled Milan and up-to-seven criteria at final histology, poor tumor differentiation, and tumor microvascular invasion negatively affected RFS by univariate analysis." (PMID 20862199, 2010). "This Cox model employed AFP, ALBU, VENINV, tumor size, new AJCC and NOTN to predict HCC prognosis (survival and DFS)." (PMID 19886989, 2009). "Patients with massive tumor, tumor size ≥ 5cm, Okuda stage II/III, AJCC stage III, Liver Child–Pugh B, pretreatment AFP level of >400 ng/ml, and MPD ≤ 80Gy or ≥ 130Gy had significantly shorter survival." (PMID 27933123, 2009). "In the analysis of prognostic factors, tumor type, tumor size, Okuda stage, AJCC stage, Liver Child-Pugh, pretreatment AFP level, and matched peripheral dose (MPD) all had significant impact on survival." (PMID 27933123, 2009). "Alpha fetoprotein (AFP), PIVKA-II (protein induced by vitamin K absence or antagonist II), desgamma-carboxy prothrombin (DCP) are tumor markers for HCC." (PMID 27956969, 2009). "Tumour markers including lactate dehydrogenase (LDH), human chorionic gonadotrophin (HCG), alpha fetoprotein (AFP) and prostate specific antigen (PSA) were normal." (PMID 16509980, 2006). "Most of the epitopes that are detectable by clinically useful tumour markers such as CEA, CA 15-3, CA 19-9, and alpha-fetoprotein are glycoproteins shed from the cell surface." (PMID 15280913, 2004). "For HCC patients with tumours approximately less than 3 cm in dimension, combining the information from PIVKAII and AFP levels significantly increases the sensitivity of diagnosis above AFP alone also." (PMID 12799630, 2003). "The distributions of the prechemotherapy levels of AFP and HCG and of the histology of the primary tumour were similar across the populations." (PMID 12644820, 2003). "However, there exist glycoforms of AFP which may be more specific for particular tumours." (PMID 10584881, 1999). "Following chemotherapy for metastatic nonseminomatous testicular cancer, 86 patients with normal serum markers AFP and HCG underwent resection of residual tumour masses (63 laparotomy, 11 thoracotomy, 12 both)." (PMID 8318413, 1993).
tumor (continued). "In ten cases surgery to remove residual abdominal masses was required on completion of chemotherapy and normalisation of tumour markers (HCG and AFP)." (PMID 1370759, 1992). "AFP immunostaining is used to confirm AFP production in tumor tissues, but not all tumors with an elevated serum AFP level show positive tissue staining due to a heterogeneous intratumoral AFP expression." (PMID 41589237, 2026). "While AFP should not be considered an independent biomarker, it holds potential as a contextual signal of aggressive tumor biology and as an adjunctive tool within integrated clinical and pathological frameworks." (PMID 41938105, 2026). "Tumor markers (HCG, CEA, AFP, CYFRA 21-1, ProGRP, anti-AchR antibody, sIL-2R) were normal." (PMID 41940047, 2026). "has indicated that plasma levels of DANCR and SNHG1 in HCC patients correlate significantly with those in cancer tissues, showing strong associations with critical clinical parameters such as microvascular invasion, invasion of the liver capsule, tumor dimensions, TNM staging, and AFP levels." (PMID 41474641, 2026). "In this context, PIVKA-II may serve as an additional tumor marker for HCC, complementing AFP in diagnosis and in the assessment of treatment efficacy." (PMID 41594225, 2026). "In addition, tumor markers, including carcinoembryonic antigen (CEA), alpha‐fetoprotein (AFP), carbohydrate antigen 125 (CA125), carbohydrate antigen 199 (CA199), and other routine laboratory tests were within normal ranges." (PMID 41584391, 2026). "In this study, YGJ significantly reduced serum AFP levels, this suggests that YGJ may have a positive impact on tumor burden." (PMID 41517800, 2026). "Tumor markers, including CEA, proGRP, AFP reflect tumor biology and systemic disease burden." (PMID 41234731, 2025). "Furthermore, AFP is known to shield HCC cells from TNF-induced cell death and promote escape of tumor cells from lymphocyte cytotoxic cells via the caspase enzyme pathways." (PMID 40430002, 2025). "Several preoperative models for predicting MVI have been proposed, incorporating biological markers (e.g., serum alpha-fetoprotein [AFP], neutrophil-to-lymphocyte ratio [NLR]) and morphological characteristics (e.g., tumor size and number, tumor burden score [TBS])." (PMID 40361345, 2025). "Non-germinomatous GCTs often secrete tumour markers such as alpha-fetoprotein (AFP) or beta-human chorionic gonadotropin (β-HCG) and typically require multimodal therapy due to relative resistance to single-modality treatment." (PMID 41523526, 2025). "Our results revealed that serum tumor markers (AFP, PSA, CA125, and CEA) remained within normal ranges without treatment-related aberrations." (PMID 41290710, 2025). "A routine CT scan did not reveal any significant changes in the tumor size, with AFP levels at 66,419 ng/mL, elevated from 34,457 ng/mL one month prior." (PMID 40755645, 2025). "circ_0027478 shows significant positive correlations with AFP, Size, TNM, and BCLC (all with p-values < 0.0001), suggesting that this circRNA might be involved in pathways related to tumor growth, metastasis, and HCC progression." (PMID 40429981, 2025). "As is often the case, typical tumor marker elevations, such as AFP and prothrombin induced by vitamin K absence-II, are not observed." (PMID 41268026, 2025). "There are standard serum tumor markers indicated in the EAU guidelines, i.e., AFP, LDH, and hCG." (PMID 40723290, 2025). "Notably, c‐HCC exhibited a significantly larger maximum tumor size compared to other HCC subtypes, and either AFP or DCP markers were found to be positive in these cases." (PMID 39846235, 2025). "Immunohistochemical staining of the tumor tissue was strongly positive for AFP while negative for hepatocytes." (PMID 40406259, 2025). "Study have found that the levels of the tumor marker AFP were lower in NASH HCC compared to non-NASH HCC cases." (PMID 40106456, 2025).
tumor (continued). "In retrospective analyses of lenvatinib use in 2L therapy, factors such as AFP < 400 ng/mL, no extrahepatic spread, Child–Pugh A, tumor number < 3, ORR under first-line treatment, and a PFS ≥ 6 months were positive prognostic factors for improved survival." (PMID 40149306, 2025). "Candidate selection assessing tumor biology through response to neoadjuvant therapy and radiographic stability, regardless of tumor burden and AFP levels, has also shown promise." (PMID 40806987, 2025). "Diagnostic assessment: the diagnostic workup revealed normal tumor markers (CA-125, CA-19-9, CEA, AFP, SCC) and a negative β-hCG." (PMID 41459358, 2025). "The patient subgroups were categorized as either low-risk or high-risk based on the median value of features with non-categorical values: prior AFP, largest tumor size, MELD score, and methRisk." (PMID 40279344, 2025). "Additionally, previous treatment history, viral etiology, AFP and PIVKA-II levels, ECOG performance status, multiple intrahepatic tumors, largest intrahepatic tumor size, PBIShi, NLR, and CRP were related to PFS." (PMID 40568585, 2025). "Being having non-viral etiology, a tumor size >5 cm, an AFP > 400 ng/mL, and a CTP score class C were all negatively associated with OS." (PMID 39735678, 2025). "Further management depends on risk stratification, based on factors such as mediastinal primary site, elevated tumor markers (AFP, HCG, LDH), and non-pulmonary visceral metastases." (PMID 40636380, 2025). "Rather than assessing tumor-specific factors in a static fashion, the varying nature of tumor markers such as AFP need to be considered." (PMID 40246743, 2025). "Tumor markers, including alpha-fetoprotein (α-AFP) and human chorionic gonadotropin (HCG), were within the normal range." (PMID 40309727, 2025). "However, IL-6 is also known to correlate with the malignancy potential of the tumor itself, such as in patients with advanced stage HCC or high AFP, and has been reported to contribute to shorter OS regardless of treatment." (PMID 39652104, 2025). "Compared to non-MTM HCC, the MTM subtype typically presents with larger tumor volumes, elevated serum alpha-fetoprotein (AFP) levels, and a significantly worse prognosis." (PMID 40875079, 2025). "Tumor markers such as cancer antigen 125 (Ca 125), Ca 19-9, human chorionic gonadotropin (β-hCG), and alpha-fetoprotein (AFP) are typically nonspecific or within normal limits." (PMID 41464707, 2025). "In addition, treatment with canagliflozin led to a significant drop in tumor marker levels, which included AFP, AFU, and CEA, potentially influencing the tumor during development." (PMID 40439888, 2025). "The Roessler liver microarray dataset provides several types of clinical information, including pathological stage, tumor‐node‐metastasis (TNM) stage, AFP, alanine aminotransferase (ALT), tumor size, overall survival rate, recurrence status, and predicted metastasis risk signature score." (PMID 39474998, 2025). "Moreover, increased tumor size, CA125 level, AFP, body weight, CA199, advanced BCLC stage and higher GLR were all associated with early recurrence (increase in the y-axis)." (PMID 41153788, 2025). "Subsequent follow-up imaging confirmed the absence of tumor recurrence or metastasis, AFP levels returned to normal, and PET-CT scans confirmed a complete metabolic response (CMR)." (PMID 41306964, 2025). "While Child-Pugh and BCLC remain standard tools for assessing liver function and tumor burden, respectively, the CRAFITY score provides complementary information by integrating systemic inflammation (via CRP) and liver function reserve (via AFP)." (PMID 41358154, 2025). "In addition, DC vaccines loaded with specific antigens such as AFP, MAGE-1, and GPC-3 enhanced IFN-γ-generating CTL responses against tumor antigens in trials combining TACE or surgical resection." (PMID 40432108, 2025).
tumor (continued). "Similarly, for OS, univariate analysis identified age, AFP serum levels, TNM stage, vascular invasion, tumor capsule, lymphatic metastasis, tumor differentiation, and the expression of CK19, Ki67, and β-catenin as important factors (all P < 0.05)." (PMID 41388520, 2025). "AFP, LDH, and b-HCG are tumor markers that are often elevated." (PMID 40686768, 2025). "By presenting AFP on MHC molecules coupled with necessary co-stimulatory signals, DEXs promote T-cell activation, break immune tolerance, and change the tumor microenvironment towards facilitating anti-tumor immunity." (PMID 41153781, 2025). "Previous study on tumor markers such as alpha-fetoprotein, carbohydrate antigen (CA) 19-9, CA 125, carcinoembryonic antigen, and prostate-specific antigen has shown that DPC is an effective delta check method for tumor markers." (PMID 39974195, 2025). "Further attempts to refine the model by incorporating additional tumour markers, such as alpha-fetoprotein (AFP) and CA125, did not yield significant improvements in predictive power." (PMID 40332145, 2025). "Taken together, these findings indicate that the serum FOLR1 level may be a potential tumor marker for detecting HCC, especially in combination with AFP." (PMID 40038575, 2025). "However, serum AFP levels remain normal in 15–30% of advanced HCC cases, and some benign diseases can also lead to elevated AFP levels." (PMID 40870838, 2025). "The non-proliferation class comprises well-differentiated tumours, often harbouring CTNNB1 (β-catenin) mutations and displaying metabolic or hepatocytic signatures with low AFP levels." (PMID 41301037, 2025). "Although AFP levels derived from different tumor biomarkers demonstrated high accuracy in determining treatment responses, pre-treatment AFP levels did not correlate with patients’ pathological features." (PMID 41002319, 2025). "On the other side, a more recent review from 2024 states that CA125 was elevated in over 80% of the patients analyzed, so other classic tumor markers like CA199, CA724, NSE, CEA, and AFP may also be elevated and used for clinical purposes." (PMID 41464736, 2025). "Given the complex pathogenesis of HCC, various diagnostic modalities are currently employed for HCC, including blood-based tumor markers such as alpha-fetoprotein (AFP) and circulating tumor DNA (ctDNA) analysis, as well as imaging techniques like ultrasound and PET/CT." (PMID 41228357, 2025). "Due to the continued uptrend of AFP raising concern for lack of control of the tumor, treatment with TARE Y90 microspheres radioembolization as a bridging therapy was initiated." (PMID 40755645, 2025). "Alpha-fetoprotein (AFP) is used as a tumor marker in the evaluation of HCC, but it should not be used in isolation for diagnosis due to its limited sensitivity and specificity." (PMID 40525070, 2025). "This tumor is characterized by rather aggressive behavior, shows a normal AFP level, and has a poor prognosis." (PMID 39953652, 2025). "PB has no specific serological tumour marker, and it has been reported that 25%–78% of patients with PB have elevated serum AFP." (PMID 40574954, 2025). "Unlike the findings of the cited studies, in this study, the maximum tumor diameter or AFP level did not significantly correlate with OS." (PMID 40427064, 2025). "Being having non-viral etiology, a tumor size > 5 cm, an AFP > 400 ng/mL, and a CTP score class C, were all significantly negatively associated with OS." (PMID 39735678, 2025). "During this period, the serum levels of tumor markers including AFP (normal range, 0-10 ng/ml), β-HCG (normal range, <5 IU/l) and LDH (normal range, 140-280 U/l) were within normal limits." (PMID 40697355, 2025). "Immunohistochemical staining of the tumor in the present case showed that the tumor tissue was negative for AFP, Glypican-3, and CK19, thus ruling out the diagnosis of HCC." (PMID 40978045, 2025). "Glycosylated proteins such as HER2, AFP, CEA, and PSA are approved tumor biomarkers clinically." (PMID 41301792, 2025).